BRCA1 (BRCA1 DNA repair associated)
Diseases named in the same sentence as BRCA1 in open-access papers (continued):
Sharing a sentence is not in itself a finding about the gene and the disease.
breast cancer (continued). "Using a combined gene set consisting of both groups of genes, we found that promoter regions with BRCA1 mutation-associated R-loops are enriched with binding sites for breast cancer-related transcription factors, such as GATA3 and FOXA1 in LP cells and SMAD2/4 and STAT6 in ML cells." (PMID 28649985, 2017). "Furthermore, gene ontology indicates that mammary neoplasm is the top disease-associated category among genes with BRCA1 mutation-associated R-loops." (PMID 28649985, 2017). "Thus, the cell death seen in BRCA1-deficient breast cancer cells with RAD52 depletion requires the HR endonuclease EEPD1." (PMID 29145865, 2017). "However, except for ovarian and breast cancers, BRCA1/2 germline mutations are less frequently observed in other malignancies, including gastric and pancreatic cancers (5%-10%), melanoma (5%), prostate and NSCLC (1%-2%)." (PMID 28055979, 2017). "Single-variant analysis suggests that BRCA1 p.Arg762Ser may be associated with breast cancer risk (OR = 7.4; 95% CI, 0.9–62.3; p = 0.06)." (PMID 28222693, 2017). "Germline BRCA1 mutations are found in almost half of the breast cancer patients." (PMID 29180619, 2017). "Recent data showing that RANKL signaling may drive BRCA1 mutation driven mammary cancer has generated interest in targeting RANKL inhibition for chemoprevention in women with BRCA1 mutation." (PMID 29088745, 2017). "BRCA1 mutation carriers also tend to develop breast cancer at a relatively young age and other studies have reported that risk of HR- CBC among those with an HR- first tumor was higher among younger women; we did not observe differences by age in our younger population." (PMID 28724391, 2017). "In particular, ER- tumors are prevalent among BRCA1 mutation carriers, which we hypothesize could explain some of the high risk of ER-/PR- CBCs following an ER-/PR- first breast cancer observed in this and in other studies." (PMID 28724391, 2017). "Furthermore, decreased BRCA1 expression results in tamoxifen resistance by altering ERα co-regulator association in breast cancer cells." (PMID 28968398, 2017). "However, when EEPD1 is also depleted in the RAD52-depleted BRCA1-deficient breast cancer cells, the synthetic lethality is completely abolished." (PMID 29145865, 2017). "The risk of breast cancer, ovarian cancer, and any type of cancer, including cervical cancer and melanoma, was first assessed in 251 female relatives of 73 carriers of founder mutations in BRCA1/2 (probands)." (PMID 28680148, 2017). "Notably, NEAT1 is found overexpressed in BRCA1-deficient breast cancer and promotes self-renewal abilities in breast cancer cells through epigenetically suppressing miR-129-5p, which targets to Wnt4." (PMID 28615056, 2017). "Furthermore, ER−/PR- breast cancers are more common among women with a BRCA1 mutation, which is involved in DNA repair pathways." (PMID 28882148, 2017). "Previous experimental studies have suggested that mechanisms other than mutations (e.g. epigenetic modifications) may alter BRCA1 expression and/or subcellular distribution in breast cancer." (PMID 28863181, 2017). "Approximately 5-10% of breast cancer cases and 10%-15% of epithelial ovarian cancer cases develop due to single gene mutations that are passed down in the family, such as the breast cancer 1 (BRCA1) and breast cancer 2 (BRCA2) genes." (PMID 28931501, 2017). "Hereditary germline BRCA1 mutations are found in around 12% of all TN breast cancers." (PMID 28851423, 2017). "MS-MLPAs were performed to assess BRCA1 and BRCA2 methylation in breast carcinoma tissues from 39 BRCA1 and 33 BRCA2 germline mutation carriers, 80 patients with sporadic breast cancer, and normal breast tissues from 5 BRCA1 and 4 BRCA2 mutation carriers and 5 nonmutation carriers." (PMID 28569220, 2017).
breast cancer (continued). "Because physical inactivity is a likely modifier of breast cancer risk in BRCA1/2-mutation carriers, carriers with children are a subgroup that may specifically benefit from lifestyle support to reduce BC risk." (PMID 27966054, 2017). "Germline mutations in the BRCA1 or BRCA2 genes are responsible for about 5% of breast cancer (BC) and are associated with a substantially increased lifetime risk of BC to 70 years old with approximately 65% and 45% of risk, respectively, in Caucasian populations." (PMID 29254229, 2017). "In addition to germline mutations in BRCA1, a smaller proportion of somatic mutations in BRCA1 were also found in primary ovarian and breast carcinomas, and subsequent studies identified the BRCA2 gene." (PMID 28525389, 2017). "BRCA1/2-mutation carriers are at high risk of breast cancer (BC) and ovarian cancer." (PMID 27966054, 2017). "Mutations in BRCA1 are associated with the onset of breast cancer." (PMID 27801815, 2016). "In cell culture models of BRCA1-mutant breast cancer, FOXC1 is associated with increased proliferation and may serve as a marker for sensitivity to PARP-inhibitor therapy with olaparib." (PMID 27708239, 2016). "Furthermore, immunohistochemistry further suggested that FOXO3 expression was significantly associated with BRCA1 status in EZH2-positive breast cancer." (PMID 27043660, 2016). "Notably it resides adjacent to BRCA1 (17q21.1) and 13 Mb from the 17q23.1 region which contains breast cancer susceptibility SNPs." (PMID 27708667, 2016). "Thus, common variations in TNFRSF11A modify the risk of developing breast cancer in BRCA1-mutation carriers, data that should be replicated in additional and larger datasets." (PMID 27881737, 2016). "We performed this study to define germline mutations in BRCA1/2 and their implication in breast cancer among young women from eastern Algeria diagnosed or treated with primary invasive breast cancer at the age of 40 or less who were referred to Anti-Cancer Center of Setif, Algeria." (PMID 26997744, 2016). "Accumulating evidence suggests that breast cancer predisposition upon inactivation of a single BRCA1 allele is caused by the so-called phenomenon of haploinsufficiency associated with heterozygosity, which results in genomic instability in breast epithelial cells." (PMID 27259235, 2016). "Interestingly, little has been done investigating genomic profiles in breast cancer tumors in association with BRCA1 expression." (PMID 26979459, 2016). "We suggest that the emergence of aggressive phenotypes observed following loss of BRCA1 function in breast cancer cells may be partly due to the de-repression of TBXA2R." (PMID 27487152, 2016). "Impact of BRCA1/2 P/LP variants on the DFS of breast cancer patients from subgroups of N0 and N1~3." (PMID 27257965, 2016). "It is of interest that the fourth signal was identified only through the meta-analysis of ER(-) breast cancer and BRCA1 mutation carriers, suggesting that this signal may be more specific to ER(-) cancers." (PMID 27459855, 2016). "Taken together, intracellular (nuclear) proteins of BRCA1-deficient breast tumor cells (e.g. TOP1) released through exosome-like EVs may represent putative candidates related to BRCA1-deficient breast cancer." (PMID 27566577, 2016). "Aberrant methylation of BRCA1 promoter is also associated with breast cancer occurrence." (PMID 27027444, 2016). "However, the index SNPs in the 2q33 locus were significantly associated with BRCA1 breast cancer (rs115635831, P=0.018; rs188686860, P=0.012)." (PMID 27117709, 2016). "In order to evaluate whether PARG depletion sensitizes cells mutated in BRCA1 by synthetic lethality, we depleted PARG by siRNA in several breast cancer cell lines either wild type or mutated for BRCA1." (PMID 27375368, 2016).
breast cancer (continued). "Hence, ALDH1, as a BCSC marker showed a specific association with BRCA1-defective breast cancers and BRCA1 has a cardinal effect on BCSC numbers and properties." (PMID 27229859, 2016). "Breast cancer risk increases drastically in individuals carrying a germline BRCA1 mutation." (PMID 27184744, 2016). "Breast cancers arising in female BRCA1 mutation carriers display characteristic pathologic features, including distinct morphology (i.e., carcinomas with medullary features) and a triple-negative phenotype [i.e., ER−, PR−, human epidermal growth factor receptor 2–negative (HER2−)] in the majority." (PMID 26857456, 2016). "For breast cancer, genetic susceptibility may be an important risk factor, as a BRCA1 founder mutation has been found in the Greenlandic population, though not studied elsewhere in the Arctic." (PMID 26765259, 2016). "In this regard, TOP1 has been described as a prominent target in BRCA1-deficient breast cancer." (PMID 27566577, 2016). "Secondary aims of the study are to investigate whether the intervention will lead to a reduction of breast cancer incidence and breast cancer mortality in BRCA1 and BRCA2 mutation carriers." (PMID 27473440, 2016). "Breast cancer of patients with germline BRCA1 mutations are often TN and BL, and their BRCA1 defects or deficiency may be involved in sporadic TNBC and BLBC." (PMID 27977696, 2016). "This gene list was then used to interrogate a TNBC microarray data set enriched for BRCA1 mutations in order to identify a molecular subgroup of breast cancers enriched for this biology and labelled as BRCA1-/NFκB+ (“NFκB on”) and all other tumours labelled as non-BRCA1-/NFκB+ (“NFκB off”)." (PMID 26943587, 2016). "In the breast cancer group, one woman carried a BRCA1 mutation and one woman a BRCA2 mutation." (PMID 27028854, 2016). "However, not all families with hereditary breast cancer exhibit the BRCA1 mutation; in fact, less than half of the families with site-specific breast cancer show an association with BRCA1 mutations." (PMID 26981296, 2016). "PfFANCJ shows 25 % identity with human FANCJ and moderate conservation throughout the central RAD3 helicase domain (DEAD2 and HelicaseC2 regions), but no conservation in the C-terminal region, which mediates interaction of human FANCJ with the breast cancer susceptibility protein BRCA1." (PMID 27809775, 2016). "Furthermore, we found high RANK expression in pre-malignant lesions and breast cancer samples from patients carrying a BRCA1 mutation." (PMID 27881737, 2016). "However, the properties of BCSCs in BRCA1-defective breast cancers and the BRCA1-deficiency-triggered molecular alterations are still largely uncharacterized." (PMID 27556296, 2016). "Based on all available data in cancer models and its physiological role in mammary epithelial proliferation in—as far as we know—every pregnant mammal, RANKL blockade could be a feasible option for the prevention of breast cancer in BRCA1-mutation carriers." (PMID 27881737, 2016). "In addition, a specific signature of methylated genes that predict breast cancer risk was recently identified in BRCA1 mutation carriers in two separate studies." (PMID 26515461, 2016). "Of the six BRCA1 mutation-associated breast cancers with information on histopathology, hormone receptor status and HER2 status, four were triple-negative (ER/PR/HER2-negative) invasive ductal carcinomas and two were atypical medullary breast cancers (ER/PR-positive, HER2-negative)." (PMID 26843898, 2016). "Furthermore, the combination of cisplatin with olaparib was investigated in a BRCA1-associated breast cancer mouse model." (PMID 27323902, 2016). "Also included are breast cancer susceptibility proteins, such as BRCA1 (FANCS) and BRCA2 (FANCD1), and SLX4 (FANCP), a scaffold for endonucleases such as XPF (FANCQ)." (PMID 27760317, 2016).
breast cancer (continued). "Whole‐exome sequencing revealed distinct BRCA1 mutations in the two alleles, one of which (c.5095C>T) generates a 35‐amino acids internal deletion and the other a one‐amino acid substitution previously reported to underlie breast cancer susceptibility." (PMID 27037238, 2016). "Women carrying BRCA1 mutations are particularly at risk of developing breast cancer at very early age and ovarian cancer during their life, while women carrying a BRCA2 mutation tend to develop breast cancer later in their life and have a significantly lower susceptibility to ovarian cancer." (PMID 26852130, 2016). "Since poly (ADP-ribose) polymerase (PARP) inhibitors are effective for treatment of breast cancer patients with BRCA1 mutation, this class of drugs may also be effective for managing breast cancer patients who overexpress LOX and carry BRCA1 mutation." (PMID 27147578, 2016). "In this study, we conducted the first comparison of the pathologic features of breast cancer arising in male and female BRCA1/2 mutation carriers, taking advantage of the previously collected pathology data from female BRCA1/2 mutation carriers assembled by CIMBA." (PMID 26857456, 2016). "However, BRCA1 mutations are much less common and 0–4% of men with breast cancer carry these mutations." (PMID 27478808, 2016). "Germline DNA CNV of BRCA1/2 is associated with the in familial and early‐onset breast cancer." (PMID 26663100, 2016). "Breast cancer patients with BRCA1 mutations frequently showed low levels of 53BP1 expression." (PMID 27494840, 2016). "All ER-negative loci combined account for ∼11% of familial relative risk for ER-negative disease and may contribute to improved ER-negative and BRCA1 breast cancer risk prediction." (PMID 27117709, 2016). "It is also important that carriers of the BRCA1 gene mutation diagnosed with breast cancer should be subjected to prophylactic surgery within less than five years from the diagnosis of breast cancer, as the risk of peritoneal cancer increases significantly after that period." (PMID 26928677, 2016). "This study suggests that a subset of women with BRCA1 mutations could be candidates for a UPA treatment as a preventive breast cancer strategy." (PMID 27246982, 2016). "We used the MLPA assay to examine whether the tumors had BRCAness, which was derived from the genomic profiles of BRCA1-mutated breast cancers." (PMID 27977696, 2016). "Interestingly, BRCA1 germline mutations of F1662 (F1662S) and M1663 (M1663K) have been identified in germline cancer patients as recorded in the Breast Cancer Information Core database." (PMID 26778126, 2016). "Thus, we undertook a prospective analysis of plasma OPG levels and breast cancer risk in 206 women with a BRCA1 or BRCA2 mutation that were unaffected by breast cancer at the time of study enrollment." (PMID 27893411, 2016). "Targeting the defective repair with DNA double strand break-inducing agents like platinum compounds might be beneficial for BRCA1 or BRCA2 mutation carriers with breast cancer." (PMID 27323902, 2016). "The excitement upon recognizing the resemblance between familial BRCA1 mutated breast cancers and certain sporadic TNBCs (BRCAness) led to the hope that similar treatment strategies might work in both sets of patients." (PMID 27077368, 2016). "The risk of developing breast cancer by age 70 is 50–70% for BRCA1/2 mutation carriers." (PMID 26967246, 2016). "Indeed, the risk of developing breast cancer in carriers of BRCA1 or BRCA2 mutation is about 45–80 %." (PMID 27129401, 2016). "The shared molecular profiles between sporadic TNBCs and BRCA1-associated breast cancer, also referred to as BRCAness, may open the way for new therapeutic strategies." (PMID 27756336, 2016). "Importantly, prophylactic salpingo-oophorectomy significantly and substantially reduces the risk of breast cancer development in BRCA1-mutation carriers (by 75%)." (PMID 27881737, 2016).
breast cancer (continued). "The potential of mammographic texture in breast cancer risk assessment has also been investigated in studies with BRCA1/2 mutation carriers, where the AUC was evaluated in terms of the performance of the texture features in predicting a woman’s risk of carrying this high-risk genetic mutation." (PMID 27645219, 2016). "Due to the pivotal role of BRCA1 in mammary gland development and the large similarity between sporadic BLBCs and hereditary BRCA1-defective breast cancers, it has been postulated that BRCA1 deficiency attenuates breast CSC (BCSC) differentiation, resulting in accumulation of BCSCs in BLBCs." (PMID 27556296, 2016). "The lifetime risk of spontaneously developing and dying from ovarian cancer are 1.39 and 1.04%, respectively; however, the incidence of developing ovarian cancer significantly increases in carriers of germline mutations, mainly with either the breast cancer gene 1 (BRCA1) or 2 (BRCA2) genes." (PMID 27242959, 2016). "Mutations in BRCA1/2 genes are identified in approximately 10% of breast cancer patients." (PMID 26515461, 2016). "These pilot results suggest that there may be a potential contribution of BRCA1 5382insC mutation to breast cancer development in the Uzbek population." (PMID 29138730, 2016). "However, only a paucity of data exists on the pathology of breast cancers (BCs) in men with BRCA1/2 mutations." (PMID 26857456, 2016). "Women carrying germline BRCA1 mutations have a cumulative risk at 70 years of 60% for breast cancer and 59% for ovarian cancer, whereas BRCA2 mutations appear to confer a similar risk of breast cancer in females (55%), but a lower risk (17%) for ovarian cancer." (PMID 27532258, 2016). "BRCA1 mutation carriers have an approximate risk of 85% to develop breast cancer." (PMID 27027444, 2016). "Thus, in mouse studies and in humans, sex hormones play a significant role in the pathogenesis of BRCA1-mutated breast cancer." (PMID 27881737, 2016). "During the follow-up time (median time was 80 months) there were 2 (2/195) cases of primary peritoneal cancer, 14 (14/195) cases of breast cancer, including 9 (9/195) primary cancers, diagnosed in our group of BRCA1 mutation carriers subjected to prophylactic salpingo-oophorectomy." (PMID 26928677, 2016). "Therefore, we comprehensively interrogated the entire HOXB13 coding sequence for mutations in 1,250 non-BRCA1/2 familial breast cancer cases and 800 controls." (PMID 27424772, 2016). "Thus, in combination with PB, ABT-888 showed increased cytotoxicity against BRCA1 mutated breast cancer cells." (PMID 27220670, 2016). "The prevalence of BRCA1/2 variants in Chinese breast cancer patients varies among studies." (PMID 27257965, 2016). "Distribution of germline or somatic BRCA1/2 variants in 507 breast cancer patients." (PMID 27257965, 2016). "About 20 % of hereditary breast cancers are caused by mutations in BRCA1 and BRCA2 genes." (PMID 26852130, 2016). "A first hint that RANK/RANKL might indeed be involved in the pathogenesis of BRCA1-mutated breast cancer came from studies of sex hormone titres in women with a BRCA1 mutation." (PMID 27881737, 2016). "These deregulations could participate in the early events of breast cancer development in BRCA1 mutation carriers." (PMID 27246982, 2016). "Furthermore, CpG island methylation of the BRCA1 gene promoter is associated with breast cancer, and can therefore be used as a biological marker of breast cancer." (PMID 27490558, 2016). "Moreover, BRCA1-mutated breast cancers are frequently triple negative and by definition lack the expression of oestrogen receptor (ER), PR and amplification of the ERBB2 oncogene." (PMID 27881737, 2016). "Recently, the concept of “BRCAness” has been introduced to investigate sporadic breast cancers with defects in the HR-mediated DNA repair pathway, which endow them with critical features also observed in hereditary breast cancers carrying BRCA1 or BRCA2 germline mutation." (PMID 27788678, 2016).